MITF (melanocyte inducing transcription factor)
Diseases named in the same sentence as MITF in open-access papers (continued):
Sharing a sentence is not in itself a finding about the gene and the disease.
tumor (continued). "However, the absence of any other melanotic marker especially SOX-10 and MITF, the absence of a relevant mitotic activity, and the prominent eosinophilic to clear cytoplasm of the tumor cells are clues to look for other tumor types." (PMID 31309284, 2020). "Importantly, the MITF‐low/proliferative subtype, characterised by an absence of the expression of immune‐response genes, had only BRAF/NRAS‐mutated samples and more tumours with CDKN2A deletions, and was significantly associated with a poorer prognosis." (PMID 30511391, 2019). "However, MITF was expressed in CD271 negative tumor areas adjacent to normal tissue in the cerebellar metastasis (Patient T1)." (PMID 28852061, 2017). "Moreover, when only subjects with tumor recurrence were considered, a significant increase of PAX3d was evident, particularly six months after their enrollment, while MITF-m and TGFB2 levels did not change." (PMID 29156734, 2017). "For the BRAFV600E;NRASQ61K culture, we did not have a paired “before” culture and hence could not assess whether PAX3 or MITF expression was increased in the culture from the acquired resistant tumor." (PMID 26977879, 2016). "Furthermore, tumours from MITF‐negative cells stayed negative and did not ‘re‐express’ MITF to significant levels." (PMID 25818589, 2015). "In tumor specimens, we also observed MITF-negative cells, which were evidently BRM/BRG1-positive." (PMID 23349796, 2013). "Finally, the gene-set #2 also contained several tumour suppressors (EPHA3 and EPHB2) and proto-oncogenes (AKT1, AURKA, ETV6, MITF and PIK3CA), which expands on the observed enrichment of the immune response and suggests that this gene-set has a critical role in breast tumorigenesis." (PMID 19826428, 2009). "In addition, recent works have identified as MITF transcriptional targets genes such as the CDK2, the hipoxia induced factor HIF1A and the hepatocyte growth factor receptor MET, all of them presenting functions that contribute to tumor development." (PMID 18211678, 2008). "We further suggest that diminution of MITF level may accompany rather than induce the invasive phenotype in tumours, and its lower level in vivo may then eventually participate in the slow proliferation of the invasive tumour subpopulations." (PMID 29369499, 2018). "Moreover, because the EDN1‐induced paracrine signalling has the potential to support both MITF‐high and AXL‐high phenotypes in acquired resistant tumours, targeting the EDN1‐EDN receptor axis could reduce the complexity seen in patients treated with MAPK inhibitor at time of progression." (PMID 28606996, 2017). "(i) Differential sensitivity to SOX10: Tumor cells with varying SOX10 expression levels exhibit unique responses, leading to distinct changes in MITF expression, particularly under nonlinear regulation." (PMID 40458894, 2025). "Although TFEB was not detectable in SPN (data not shown), TFE3 and MITF were both highly expressed in SPN compared to other tissue types, including tumor and benign tissues (cohorts 1/2)." (PMID 41310888, 2025). "In the Netherlands, observed putative PGVs in dominant genes that do not match the tumor type (ATR, CHEK2 (3x), SDHA and MITF) are normally not reported back to the patient, except if there is a matching personal and/or familial history." (PMID 41168197, 2025). "We observed a high concordance with immune cell-related but not tumor cell-related genes (NGFR, MITF, MLANA, SLC45A2) and correlation with expression of PDCD1LG2 and SUSD3, irrespective of the side of metastasis." (PMID 38386085, 2024). "In contrast, the tumor cells were nonreactive for SF-1, inhibin alpha, desmin, HHF35, HMB45, Melan A, MITF, c-kit, DOG1, cytokeratin AE1/AE3, h-caldesmon, STAT6, CD68, MDM2, CDK4, c17, DHEAST, 3BHSD, CD31, Factor 8, and ERG." (PMID 34797454, 2021).
tumor (continued). "Tumor cells were nonreactive for SF-1, inhibin alpha, desmin, HHF35, HMB45, Melan A, MITF, c-kit, DOG1, cytokeratin AE1/AE3, h-caldesmon, STAT6, CD68, MDM2, CDK4, c17, DHEAST, 3BHSD, CD31, Factor 8, and ERG." (PMID 34797454, 2021). "In a fourth lesion the tumor expressed NFATc2 and ZEB1, but was negative for N-Cadherin and expressed MITF." (PMID 30710146, 2019). "In three out of four lesions the tumor was positive for NFATc2, ZEB1 and N-cadherin, but lacked MITF." (PMID 30710146, 2019). "HT144 cells, with a considerably lower level of MITF protein, form slower growing tumors compared to MM649 when xenografted into BALB/c Foxn1nu mice (time to approximately 50 mm3 tumor volume; HT144 – 14 days, MM649 – 7 days; data not shown)." (PMID 28883623, 2017). "However, the role of MITF is complex, since both high and low levels of MITF can be found in cells with acquired resistance, even within the same tumor in different clones, suggesting that MITF may or may not be required for the acquisition and maintenance of resistance to MAPKi." (PMID 27596438, 2016). "We found CD271 expression in all metastases investigated and respective xenograft tumors albeit with varying intensities and limited to tumor-initiating cells, negative for HMB45 and MITF." (PMID 24799129, 2014). "All the tumours expressed nuclear and occasionally cytoplasmic P-ERK1/2, however, both signals were by far more abundant in the GHM samples (80.2% ±8.5 vs. 7.6% ±21.3 in Grey and non-grey MITF+ cells, respectively)." (PMID 25413220, 2014). "In addition, a few resistant tumours do not restore ERK phosphorylation but seem to bypass the MAPK pathway through the activation of a more downstream oncogenic output through GPCR-cAMP-CREB signalling and amplification of MITF." (PMID 35159327, 2022).
cancer (200 papers, 2008 to 2026). A tumor composed of atypical neoplastic, often pleomorphic cells that invade other tissues. "Pathogenic or likely pathogenic variants in cancer-associated genes were identified in 37 (6.8%), most frequently in MITF, DICER1, and BRCA2, while 43 (7.9%) harbored variants in NDD-related genes, including DHCR7, POLG, and ARSA." (PMID 41844650, 2026). "Activation of Wnt/β-catenin signaling and MITF, a β-catenin transcriptional target, are implicated as drivers of BRAFi resistance in cancer cells carrying the BRAFV600E mutation." (PMID 40558548, 2025). "Looking at the gene expression analysis in the Volcano plot, the most upregulated genes in UM with low MITF have already been associated with increased malignancy in other cancer types or are related to monosomy 3 in UM." (PMID 37240204, 2023). "MITF was significantly participated in cell differentiation, negative regulation of apoptotic process, pathways in cancer, and implicated in cancer." (PMID 36513974, 2022). "For example, it is quite well established that altered regulation of MiTF/TFE proteins can be linked to cancer development." (PMID 35665902, 2022). "Through proteome profiling, the attenuation of the microphthalmia-associated transcription factor (MITF) signaling pathway was linked to the observed anti-cancer effects of ACY-1215." (PMID 35159049, 2022). "This study investigates the functional role of MITF in cancer and the molecular mechanism underlying disease progression in ccRCC." (PMID 34208068, 2021). "The activation of the pLysRS-Ap4A-regulated MITF pathway is the main hallmark in both cancer and immune cells." (PMID 34070694, 2021). "This track aims at dependencies of cancer cells on tissue and cell type-specific survival factors, e.g., the microphthalmia-associated transcription factor (MITF)-inhibitor ML329, described by Faloon and colleagues." (PMID 33917267, 2021). "Among them, up-stream tyrosine kinase receptor ErbB-2, Rab-like protein 6 (RABL6), microphthalmia-associated transcription factor (MITF), which are involved in progression and development of several types of cancer were predicted to be suppressed." (PMID 31671612, 2019). "We cannot state with certainty that the P/LP BRCA2, CHEK2, HOXB13, and MITF variants contributed to the patient's cancer, these might also be secondary findings." (PMID 38415346, 2024). "The family history was unremarkable for MITF-associated cancer types." (PMID 37507557, 2023). "Interestingly, the downregulation of two genes from module 106 are associated with cancer cell phenotype switching: the microphthalmia-associated transcription factor (MITF) and the POU domain transcription factor POU3F2 (better known as BRN2)." (PMID 35631574, 2022). "The associated cancer risks with MITF variants (observed in 10 participants) are not well defined and hence we suggest that further evidence is required before incorporating MITF into RCC panels." (PMID 35441217, 2022).
cancer (continued). "We have previously reported a decrease in degranulation and cytokine secretion following the inhibition of pyruvate dehydrogenase (PDH) either by CPI-613 (PDH inhibitor/anti-cancer drug) or through its interaction with mitochondrial microphthalmia-associated transcription factor (MITF)." (PMID 35159398, 2022). "Enhanced levels of protein synthesis and metabolic activities could allow cancer cells to cope with the metabolic demand related to the high proliferative rate associated with MITF." (PMID 35682684, 2022). "Thus, proteomic analysis revealed that MITF was associated with cancer signaling pathways in OvCa cells." (PMID 33371469, 2020). "With the perturbed cellular kinome being the single most unifying feature of highly heterogeneous cancers, we hypothesized an invariable association of MITF-engendered resistance with a deregulated kinome." (PMID 26962685, 2016). "However, risk factors common for both cancers are only partially explained and include mutations in MITF gene." (PMID 25945350, 2015). "TFE3- and TFEB-associated cancers are generally considered difficult to treat through chemotherapy or irradiation, which may be related to the activation of survival factors, similar to MiTF." (PMID 26872381, 2016). "Although numerically modest, PTSPs were recurrent across samples and included products from cancer/immune genes (e.g., MITF, DAPK1, HLA-E), with synthetic-peptide validation and evidence of immunogenicity." (PMID 41293269, 2025). "It was enriched relative to other cancers for distal location, SBS18 and the E. colipks+ signatures SBS88 and ID18, although not for any specific driver mutation (except the rare driver MITF)." (PMID 39112709, 2024). "There is strong evidence indicating that MITF is involved in several diseases, including cancer, although the precise mechanisms and roles of MITF in these diseases remain largely unclear." (PMID 38351314, 2024). "Recurrent P/LP variants were identified in individuals diagnosed with cancer from distinct families, in the following cancer genes: BRCA1 (n = 3), LZTR1 (n = 3), HNF1A (n = 2), CHEK2 (n = 2), MITF (n = 2), and CHD4 (n = 2)." (PMID 37377903, 2023). "MITF has been identified as an oncogene, meaning that it can promote the development of cancer when it is dysregulated." (PMID 37504268, 2023). "TGF-β is a well-known inducer of EMT and invasiveness in cancer and it was identified as a potent repressor of MITF." (PMID 35406721, 2022). "Taken together, our findings indicate that MAPK1 enhances the cancer-promoting characteristics of the MITF protein via serine 73 phosphorylation." (PMID 36268034, 2022). "CREB1 activates MITF transcription, and MAPK1 enhances the activity of MITF via phosphorylation at serine 73, boosting the cancer-promoting effect of MITF in GC." (PMID 36268034, 2022). "Follow-up studies indicated that miR-585-5p targets the downstream molecules CREB1 and MAPK1 to regulate the transcriptional and post-translational regulation of MITF, respectively, thus controlling its expression and cancer-promoting activity." (PMID 36268034, 2022).
cancer (continued). "Three proteins (PLAU, ZEB1, and MITF) were involved in the “transcriptional misregulation in cancer”." (PMID 34408977, 2021). "lncRNA LINC00518, under potential transcriptional control by MITF, regulates an RNA–RNA network promoting cancer-related processes." (PMID 34988221, 2021). "MITF is annotated in the Cancer Gene Census as an amplification driver gene and a likely oncogenic driver in OncoKB." (PMID 34313788, 2021). "MITF promotes the survival, proliferation and differentiation of melanocytes, and is involved in cancer progression." (PMID 34208068, 2021). "The GFP-labeled ES-2 cells transfected with control siRNA or siRNA against MITF were seeded on HPMCs, and the migration of cancer cells on HPMCs was continuously observed via time-lapse images." (PMID 33371469, 2020). "HGF can also be secreted by the cancer cells themselves and exert its effect in an autonomous manner to regulate the expression of its own receptor in a MITF-dependent manner." (PMID 33276788, 2020). "The AP1 TF binding motifs have been shown to overlap with the microphthalmia-associated transcription factor (MITF), which is a master regulator of melanocytes, and AP1 has been shown to play a critical role in cancer invasion." (PMID 32079144, 2020). "The results obtained suggest that LINC00518, under potential transcriptional control by MITF, regulates an RNA–RNA network promoting cancer-related processes (i.e., cell proliferation and migration)." (PMID 33371395, 2020). "MITF has several targets and we queried a selected handful of them in this study, based on their role in cancer therapy resistance." (PMID 31547367, 2019). "Depletion of MITF can reduce proliferation through G1-arrest with increased expression of cancer stem cell markers." (PMID 29881716, 2018). "The resulting transcription factors were the candidates for MITF regulation in our investigated cancer cell samples." (PMID 26927636, 2016). "The discriminant isoforms in the invasive phenotype (MITF–) were enriched for multiple cancer hallmarks, whereas the proliferative phenotype (MITF+) presented enrichment only for activation of KRAS signaling, which does not appear in the invasive phenotype." (PMID 27535130, 2016). "The α-melanocyte-stimulating hormone (α-MSH) signal transduction involving Wnt/β-catenin, c-Kit, and microphthalmia-associated transcription factor (MITF), a known pathway to produce melanin, has been demonstrated as one of cancer stem cell characteristics." (PMID 23762150, 2013). "β-catenin/TCF/LEF transcription activity also regulates expression of c-Myc, TP63 isoform ΔN (ΔNp63), microphthalmia-associated transcription factor (MITF), limb bud and heart development homolog (LBH), survivin and c-Jun in various cancer models 44–49." (PMID 23490077, 2013). "We find that somatic mutations create or disrupt putative miRNA target sites in the 3′UTRs of many genes, including several genes, such as MITF, EPHA3, TAL1, SCG3, and GSDMA, which have been previously associated with cancer." (PMID 23091610, 2012). "Most likely, MITF plays both cancer-promoting and cancer-inhibiting roles alternated by the expression level and/or activity." (PMID 22046555, 2011). "To characterize cancer cell signatures in MBMs, we compared the expression of two established programs: the AXL-high program (associated with invasiveness and drug resistance) and the MITF-high program (defined by melanocyte lineage markers including MITF)." (PMID 41284647, 2025). "Moreover, in cancer cell lines, RAD51 is associated with the regulation of the autophagy pathway and works together with E-box proteins such as USF1, USF2, and MITF to regulate the expression of autophagy-related genes." (PMID 40746357, 2025).